C4A-AS1 (C4A antisense RNA 1)
Gene: Long non-coding RNA gene on chromosome 6 (31,999,976 to 32,003,521, reverse strand). Ensembl gene ENSG00000233627.
Homologues: Paralogues in human: C4B-AS1 (100% identical).